GCGR (glucagon receptor)
Diseases named in the same sentence as GCGR in open-access papers (continued):
Sharing a sentence is not in itself a finding about the gene and the disease.
diabetes (continued). "Inhibition of GCGR activity represents a potential therapeutic approach for reducing excess glucose production in diabetes mellitus." (PMID 28775305, 2017). "With the advantages of small size, high binding affinity, good stability, lack of immunogenicity, easy synthesis and modification, aptamer GR-3 against GCGR is a promising probe molecule which is a potential tool for the treatment of diabetes mellitus." (PMID 28775305, 2017). "With the advantages of small size, high binding affinity, good stability, lack of immunogenicity, and easy synthesis, aptamer GR-3 against GCGR can be a promising tool with the potential to attenuate hyperglycemia in diabetes mellitus." (PMID 28775305, 2017). "Glucagon receptor inhibition decreases hyperglycemia in various animal models of diabetes, as well as in patients with type 2 diabetes." (PMID 27092792, 2016). "In case of near-total insulin deficiency, transient glucagon receptor blockade could also serve as a means to increase the α-cell mass before triggering insulin production in these cells, a strategy that might be envisioned as a novel therapy to treat diabetes." (PMID 27092792, 2016). "Accordingly, immunoneutralization of glucagon or genetic deletion of the glucagon receptor improved glucose homeostasis in animal models of diabetes." (PMID 23744070, 2013). "We and others have generated inhibitory monoclonal antibodies targeting GCGR that are potential therapeutics for the treatment of diabetes." (PMID 24189067, 2013). "Deletion of the glucagon receptor in mice resulted in protection from streptozotocin (STZ)-induced diabetes and severe hyperglycemia appeared when the knock-out was reverted by adenoviral glucagon receptor expression." (PMID 23744070, 2013). "Antagonism of the glucagon receptor (GCGR) thus represents a potential approach to diabetes treatment." (PMID 23185367, 2012). "Recent research has shown that glucagon receptor agonism (in combination with glucagon-like peptide 1 receptor [GLP-1R] agonism) rather than antagonism is more promising as a therapeutic intervention of combating diabetes and other metabolic disorders." (PMID 40280422, 2025). "Preclinical studies suggest that GCGR/GLP-1R/glucose-dependent insulinotropic polypeptide (GIP) receptor triple agonists may also prove useful for the therapy of diabetes and obesity." (PMID 38879678, 2024). "Glucagon receptor (GCGR) is a class B1 G-protein-coupled receptor that plays a crucial role in maintaining human blood glucose homeostasis and is a significant target for the treatment of type 2 diabetes mellitus (T2DM)." (PMID 39125959, 2024). "Taken together, these results suggested that treatment with GCGR mAb could effectively attenuate the diabetes‐induced upregulation of CPT1B, OPA1, and MFN1, and oxidative stress in CMECs." (PMID 37596940, 2023). "In this regard, the development of a GCGR inhibitor is significant, especially in understanding how this inhibitor interacts with GCGR to inhibit the downstream signaling, eventually blocking the development of diabetes." (PMID 37586587, 2023). "In addition, some recent observations, coupled with earlier work, suggest that GCGR blockade can also promote recovery of functional beta-cell mass, with obvious additional benefits for diabetes." (PMID 36005280, 2022). "The study has shown that, in diabetics, decrease in insulin is not as harmful as an increase in glucagon, as insulin deficient animals that were simultaneously knocked out of the glucagon receptor were normoglycemic." (PMID 35211170, 2022). "Therefore, antagonists of the glucagon receptor have been proposed as glucose-lowering drugs in diabetes." (PMID 34801547, 2022). "The glucagon receptor (GCGR) is a potential target for diabetes therapy." (PMID 36334626, 2022). "The compensatory excessive glucagon production may limit the application of GCGR antagonism for diabetes therapy." (PMID 36334626, 2022).
diabetes (continued). "The absence of a GCGR polymorphism (Gly40Ser) at one site does not rule out mutations associated with susceptibility to diabetes in other regions." (PMID 35784565, 2022). "Designing drugs with the optimal combination of GLP-1R and GCGR activation is important and may confer greater benefits in reversing diabetes than GLP-1R activation alone, as demonstrated recently." (PMID 34572144, 2021). "We also conducted experiments to determine whether P18 could act as an antagonist at the GCGR as blocking the action of glucagon has been proposed as a novel strategy in the treatment of various forms of diabetes." (PMID 31330984, 2019). "Nevertheless, the bihormonal hypothesis has made blockade of the glucagon receptor a potential treatment for diabetes." (PMID 29412829, 2018). "Direct measurement of IR, IGFR, and glucagon receptor-glycation might provide more accurate and sensitive means for evaluating the effects of hyperglycemic episodes in diabetes than does hemoglobin A1C." (PMID 29207492, 2017). "Elevated glucagon secretion and GCGR activity was observed in diabetes patients." (PMID 26075596, 2015). "Therefore antagonists towards the GCGR are considered to be a potential strategy to treat diabetes leading to the development of a number of GCGR antagonists." (PMID 26075596, 2015). "Most of the available glucagon receptor based inhibitors for the treatment of type 2 diabetes mellitus fall in the category of glucagon neutralizing antibodies or small molecular weight glucagon receptor antagonists which have been shown to efficiently terminate glucagon receptor action." (PMID 25521597, 2014). "We present a model for the allosteric inhibition of GCGR by a monoclonal antibody that may form the basis for the development of allosteric modulators for the treatment of diabetes and other class B GPCR-related diseases." (PMID 24189067, 2013). "Hypoglycemia in therapy of diabetes mellitus is a major concern, but even overnight fasting of mice with genetically deleted glucagon receptor only led to marginally lower blood glucose levels as compared with wild type animals, without occurrence of hypoglycemia." (PMID 23744070, 2013). "In the mouse, targeted disruption of the GCGR gene results in reduced plasma glucose concentrations and treatment with GCGR antisense oligonucleotides has an antihyperglycemic effect in rodent models of diabetes." (PMID 23185367, 2012). "In the present study, we provide evidence that PDAC-associated diabetes is distinguished by a global downregulation of key islet hormones (INS, GCG) as well as β-cell-enriched transcription factors such as MAFA and PAX4, and hormone receptors such as GCGR, SSTR3 and SSTR5." (PMID 40244011, 2025). "Additionally, AM TCRs did not mimic diabetes-associated proteins such as insulin, the insulin receptor, glucagon, or the glucagon receptor." (PMID 38339075, 2024). "Volagidemab (REMD-477) is a humanized glucagon receptor monoclonal antibody (GCGR mAb) that is being investigated for its therapeutic potential in diabetes because it antagonizes the glucagon receptor and may be able to prevent these negative effects of hyperglucagonemia." (PMID 37296593, 2023). "Second, we found that GCGR mAb significantly increased the number of CMECs in the diabetic mice, indicating that improvement of cardiac microvascular function by GCGR mAb might account for the amelioration of the diabetes‐induced cardiac diastolic dysfunction." (PMID 37596940, 2023). "Indeed, alpha-to-beta-cell lineage conversion is enhanced in GCGR KO mice, and more recently, human alpha-cells were shown to be capable of reprogramming into glucose-sensitive insulin-secreting cells to help ameliorate diabetes in mice." (PMID 36005280, 2022). "Whether and how GCGR signaling changes during diabetes is unknown." (PMID 33935974, 2021).
diabetes (continued). "Glucagon receptor (GCGR) is a secretin-like (class B) family of G-protein coupled receptors (GPCRs) in humans that plays an important role in elevating the glucose concentration in blood and has thus become one of the promising therapeutic targets for treatment of type 2 diabetes mellitus." (PMID 26236379, 2015). "While glucagon receptor (GCGR) antagonism ameliorates hyperglycemia and elicits beta cell regeneration in pre-clinical models of diabetes, it also promotes alpha and delta cell hyperplasia." (PMID 39433176, 2024). "From a multi-target perspective, the elevation in cAMP levels may not solely result from GLP-1R activation but could also involve other diabetes-related therapeutic targets such as DPP4, GIPR, and GCGR." (PMID 41373699, 2025). "Cotadutide is a dual glucagon-like peptide 1 and glucagon receptor agonist under development for the treatment of non-alcoholic steatohepatitis and type 2 diabetes mellitus (T2DM) and chronic kidney disease." (PMID 38066113, 2023). "Gcgr -/- mice were designed to further understand the role of GCGR in the development of diabetes; these mice do not respond to glucagon at any concentration, and their fasting blood glucose levels are lower than those of wild-type mice." (PMID 35784565, 2022). "Therefore, we suggest that the changes in the effects of GCGR and GLP-1R induced by metabolic stress should also be considered when designing GCGR- and GLP-1R-combined agonists for the treatment of diabetes." (PMID 34572144, 2021). "To assess whether induced glucagon receptor blockade prevents diabetes upon near-total β-cell ablation, we pre-treated adult RIP-DTR mice with the anti-GCGR mAb for 3 weeks, and then injected them with DT." (PMID 27092792, 2016). "The importance of glucagon signaling in diabetes was recently highlighted in studies performed with glucagon receptor knockout (Gcgr-/-) mice and in animals lacking α-cells due to pancreatic aristaless-related homeobox (Arx) deficiency." (PMID 27092792, 2016). "Management of diabetes without any side effects is still a challenge to the medical system, and the search for a new and effective natural GCGR antagonist is an important area for the treatment of type 2 diabetes." (PMID 26236379, 2015). "GCGR mAb treatment in PANIC-ATTAC mice, which triggers caspase-8–mediated apoptosis specifically within the pancreatic β-cell, stimulates α-cell to β-cell conversion, leading to sustained improvements in glycemic control and effectively curing diabetes in this model." (PMID 39057094, 2024). "Taking a pharmacokinetic approach, non-peptide antagonists at the glucagon receptor have been developed that are per-orally available and might play a role in treating diabetes." (PMID 37629010, 2023). "However, other studies have shown that fulminant diabetes will still develop in mice that lack insulin despite the absence of GCGR signaling." (PMID 37586587, 2023). "The therapeutic potential of GCGR is not fully recognized and should be a basis of further studies; however, the established animal models provide an effective means for the development of strategies to reduce the incidence of diabetes." (PMID 35784565, 2022). "In our study, we hypothesized that off-target interactions of specificdrugs with gut hormone receptors GLP1R, GIPR and GCGR could be a way to compensate for the negative influence of each on glucose homeostasis leading to drug-induced diabetes." (PMID 30682072, 2019). "Because expression of the glucagon receptor in the liver alone is sufficient to produce severe diabetes in glucagon receptor-null mice lacking functional β-cells, suppression of glucagon-induced hepatic glucose output would appear to be a good target for T2D therapy." (PMID 25982967, 2015).
type 2 diabetes (59 papers, 2013 to 2026). "Plasma GLP-1 and GLP-2 levels are markedly increased in individuals with type 2 diabetes treated with a GcgR antagonist as well as in GcgR-deficient mice." (PMID 39064713, 2024). "Cotadutide, a once-daily GLP-1 and glucagon receptor dual agonist, demonstrated optimal weight loss and glycaemic control in a 48-day phase 2a study in Japanese adults with type 2 diabetes." (PMID 34430840, 2021). "We determined associations of glucagon receptor variants and proglucagon with BMI, type 2 diabetes and liver fat (quantified by liver MRI) and performed survival analyses to investigate if elevated proglucagon predicts type 2 diabetes development." (PMID 38705923, 2024). "To test if the association between plasma proglucagon and type 2 diabetes and BMI, respectively, was dependent on the glucagon receptor genotype, we performed logistic and linear models stratified on the variant groups with inclusion of the interaction term proglucagon×genotype." (PMID 38705923, 2024). "Several pharmaceutical companies have pursued development of GCGR antagonists (using various molecular formats), which have been shown to improve glucose regulation without increasing the risk of hypoglycaemia in patients with type 1 diabetes as well as those with type 2 diabetes." (PMID 36404376, 2023). "Because of its role in regulating blood glucose levels, GCGR is a therapeutic target for treating type 2 diabetes." (PMID 37586587, 2023). "In this study, we demonstrated that inhibition of glucagon activity by GCGR mAb not only improved blood glucose control but also increased pancreatic beta cell mass and proliferation in mouse models of type 2 diabetes." (PMID 36331598, 2023). "The db/db mice and high-fat diet (HFD)+streptozotocin (STZ)-induced mice with type 2 diabetes were treated with antagonistic GCGR monoclonal antibody (mAb), and the metabolic variables and islet cell quantification were evaluated." (PMID 36331598, 2023). "Our findings demonstrate that liver-derived FGF21 is involved in the GCGR antagonism-induced beta cell regeneration in a mouse model of type 2 diabetes." (PMID 36331598, 2023). "First, we investigated the effects of GCGR mAb on beta cell mass and function in two mouse models of type 2 diabetes." (PMID 36331598, 2023). "Antagonistic GCGR monoclonal antibody (mAb) has a strong hypoglycaemic effect in mouse models of type 1 diabetes and type 2 diabetes and in people with diabetes." (PMID 36331598, 2023). "In conclusion, our study demonstrates that GCGR mAb not only ameliorates hyperglycaemia but also increases functional beta cell mass in mouse models of type 2 diabetes, and that these effects are at least partly mediated via liver-derived FGF21." (PMID 36331598, 2023). "Glucagon receptor (GCGR) antagonism ameliorates hyperglycaemia and promotes beta cell regeneration in mouse models of type 2 diabetes." (PMID 36331598, 2023). "Here the authors report that IBI362 (LY3305677), a balanced once-weekly GLP-1 and glucagon receptor dual agonist, showed favourable safety and tolerability in Chinese patients with type 2 diabetes in a randomized controlled phase 1b clinical trial." (PMID 35750681, 2022). "Conversely, pharmacological studies reveal that treatment with the glucagon receptor antagonist LY2409021 increased hepatic fat content in individuals with type 2 diabetes." (PMID 33275161, 2021). "The receptors for the glucagon-like peptide-1 (GLP-1R), glucose-dependent insulinotropic polypeptide (GIPR), and glucagon (GCGR) are major pharmacological targets in metabolic diseases such as type 2 diabetes (T2D) and obesity." (PMID 33268378, 2021). "Inhibition or inactivation of GCGR is shown to lower blood glucose in preclinical models of type 1 and type 2 diabetes." (PMID 31979106, 2020). "Unimolecular dual agonists for the glucagon-like peptide 1 receptor (GLP1R) and glucagon receptor (GCGR) are emerging as a potential new class of important therapeutics in type 2 diabetes (T2D)." (PMID 33028880, 2020).
type 2 diabetes (continued). "The inactive conformations of glucagon receptor (GCGR) are widely reported by crystal structures that support the precision structure for drug discovery of type 2 diabetes." (PMID 31921774, 2019). "At the same time, other literature reports that glucagon can bind to its receptor GCGR to regulate glucose levels and fatty acid oxidation in patients with type 2 diabetes by regulating the level of cAMPs and pka-independent pathways." (PMID 31341893, 2019). "As type 2 diabetic hyperglucagonaemia contributes to the hyperglycemic state of patients with type 2 diabetes (T2D), inhibition of glucagon receptor signaling has been investigated as glucose-lowering therapy in T2D patients." (PMID 31068828, 2019). "This study does not elucidate the dynamical conformation characteristics between the GCGR and an antagonist, which can decrease the blood sugar level to treat type 2 diabetes mellitus." (PMID 31921774, 2019). "In type 2 diabetes model mice, there were distinct differences in tumor growth between control and GCGR knockdown clones, even though the concentrations of plasma blood glucagon in mice are much lower than in cell culture media used for in vitro studies." (PMID 29535833, 2018). "The present observations provide experimental evidence that hyperglucagonemia in type 2 diabetes promotes colon cancer progression via GCGR-mediated regulation of AMPK and MAPK pathways." (PMID 29535833, 2018). "In subsequent years, several small molecule glucagon receptor antagonists were developed and shown to act as powerful (oral) antidiabetic agents in both preclinical and clinical studies of type 2 diabetes." (PMID 28323959, 2017). "GCGR based inhibitors for the treatment of type 2 diabetes are either glucagon neutralizers or small molecular antagonists." (PMID 26236379, 2015). "GCGR based inhibitors for the treatment of type 2 diabetes are either glucagon neutralizing antibodies or small molecular antagonists." (PMID 26236379, 2015). "The inhibition of glucagon-GCGR interaction has been reported to control the hepatic glucose overproduction that makes it an attractive therapeutic strategy for the treatment of type II diabetes mellitus." (PMID 25521597, 2014). "Inhibiting the interaction between glucagon and its receptor has been reported to control hepatic glucose overproduction and thus GCGR has evolved as an attractive therapeutic target for the treatment of type II diabetes mellitus." (PMID 25521597, 2014). "Elevated glucagon levels and increased hepatic glucagon receptor (GCGR) signaling contribute to hyperglycemia in type 2 diabetes." (PMID 24189067, 2013). "Therefore, the relative role of a direct blockade of glucagon signaling in the liver and the indirect effects of GCGR blocker treatment leading to an elevation of plasma GLP-1 on the improvement of hyperglycemia in type 2 diabetes remains to be clarified." (PMID 38265288, 2024). "Inhibition of GCGR in type 2 diabetes patients also increased plasma ALT activity." (PMID 36404376, 2023). "Interestingly, GCGR has also been reported to play an important role in regulating type 2, or noninsulin-dependent diabetes mellitus, by reducing its expression or activity through GCGR antagonist." (PMID 37586587, 2023). "Indeed, inhibition of glucagon signalling by treatment with a glucagon receptor antagonist has shown favourable effects on glucose metabolism in individuals with type 2 diabetes." (PMID 33275161, 2021). "However, in our patients with type 2 diabetes, it is more likely that the fasting glucose levels are maintained by (elevated) glucagon levels, as clearly demonstrated in experiments with glucagon receptor antagonists." (PMID 34382579, 2021). "However with the recent elucidation of the crystal structure of 7 TM domain of glucagon receptor, a rational drug design approach can be applied for identification of potent agents against type 2 diabetes." (PMID 25521597, 2014).